ENSG00000288843 (novel transcript)
Gene: Long non-coding RNA gene on chromosome 20 (41,623,485 to 41,715,725, reverse strand). Ensembl gene ENSG00000288843.
Gene Ontology:
Biological process: RNA processing
Cellular component: nucleolus